SIRT1 (sirtuin 1)
Diseases named in the same sentence as SIRT1 in open-access papers (continued):
Sharing a sentence is not in itself a finding about the gene and the disease.
inflammatory bowel disease (15 papers, 2020 to 2025). A spectrum of small and large bowel inflammatory diseases of unknown etiology. "SIRT1 emerges as a promising biomarker for relapses and a viable therapeutic target across a range of autoimmune diseases (ADs), including inflammatory bowel disease (IBD)." (PMID 38482749, 2024). "It has been shown that inhibition of Nlpr3 inflammatory vesicles by activation of Sirt1 acts on radiation-induced inflammatory bowel disease in mice." (PMID 36641776, 2023). "Conversely, one study showed in inflammatory bowel disease, SIRT1 expression is upregulated, and specific inhibition of SIRT1 significantly reduces ROR-γt mRNA levels in Th17 cells, leading to a decrease in Th17 cell proportion and alleviation of local inflammation." (PMID 40416964, 2025). "The silent information regulator 1 (SIRT1) has a dual role along with possible mechanisms in the different experimental models of inflammatory bowel disease (IBD)." (PMID 40076434, 2025). "For example, in inflammatory bowel disease (IBD), depletion of NAD+ decreased SIRT1 activity and led to increased acetylation of PGC1α, contributing to mitochondrial dysfunction." (PMID 39852780, 2024). "SIRT1 RNA and protein expression are reduced in whole intestinal biopsies and the lamina propria mononuclear cells of patients with inflammatory bowel disease (IBD)." (PMID 33513830, 2021). "In colonic biopsies from patients with inflammatory bowel disease (IBD), SIRT1 was downregulated by TNF-α and IL-21 in the mucosa." (PMID 33414704, 2020).
lung disease (15 papers, 2015 to 2026). "Our study provides new insights into the regulatory role of the SIRT1/miR-34a-5p/ADAM17 axis in HIV-associated lung disease, particularly in impaired mucociliary clearance (MCC) and inflammation." (PMID 39682757, 2024). "On the other hand, sirtuin 1 (SIRT1) is an NAD+-dependent lysine deacetylase associated with cardiovascular and pulmonary diseases including fibrosis." (PMID 38111379, 2023). "Previous studies have demonstrated that sirt-1 has therapeutic effects in lung diseases because sirt-1 modulates the pro-oxidative/antioxidative balance." (PMID 35115954, 2021). "Extant basic and translational studies have reported the interaction effects of air pollution and SIRT1 on the incidence or progression of pulmonary diseases and cardiovascular diseases." (PMID 33715628, 2021). "It has been showed that BRD4 inhibitor JQ1 upregulated SIRT1 and alleviated inflammatory responses in a cellular model of lung disease." (PMID 32457617, 2020). "Previous in vitro and in vivo researches suggest that SIRT1 negatively regulates NF-κB-proinflammatory axis in lung disease, including COPD and allergic asthma." (PMID 31299012, 2019). "After the finding of SIRT1 upregulation and activation, we analyzed the biological effects of this pathway in A549 cells, a lung disease cell line where SIRT1 is known to have beneficial anti-inflammatory effects." (PMID 26212199, 2015). "We have also shown that SIRT1 upregulation and bromodomain inhibition have anti-inflammatory effects in a lung disease model, human A549 alveolar epithelial cells, and that both BRD2 and BRD4 bromodomain proteins are involved in these processes." (PMID 26212199, 2015). "Additionally, previous experimental studies observed that air pollution and SIRT1 have an interactive effect on pulmonary diseases, cardiovascular diseases." (PMID 33715628, 2021). "We found that propofol enhanced SIRT1 expression in NR8383 cells, suggesting that propofol could be used to inhibit pulmonary disorders by inducing SIRT1." (PMID 33260147, 2020). "A combination of BET inhibitors (JQ-1 49) and SIRT activators (SRT1720, 51) was found to alleviate inflammatory response due to the upregulation of SIRT1 by the BETi JQ-1 49, thus reversing the pro-inflammatory response to SIRT1 inhibition in a cellular lung disease model." (PMID 27752293, 2016). "Moreover, we observed that BET inhibition functionally reversed the pro-inflammatory effect of SIRT1 inhibition in a cellular lung disease model." (PMID 26212199, 2015). "The anti-inflammatory effects of BCX and 3OH-BA10C were associated with the upregulation of sirtuin 1 (SIRT1), an NAD+-dependent protein/histone deacetylase that has been implicated in various biologic processes, such as metabolism, inflammation, and immune function in lung disease." (PMID 36771049, 2023). "SIRT1 functions as a protector from PM exposure, whereas PIR acts as a predictor of PM-induced pulmonary disease." (PMID 31299012, 2019). "For example, in pulmonary diseases such as COPD, oxidative stress, and, in particular, augmented H2O2 concentration via phosphoinositide-3-kinase (PI3K) signaling, increases miR-34a levels, with the consequent reduction in both mRNA and the amounts of sirtuin-1 and -6 (SIRT1/-6) deacetylases." (PMID 40573184, 2025).
non-alcoholic steatohepatitis (15 papers, 2020 to 2025). "In the same context, Hua and co-workers proposed NGN as an activator of SIRT1 in the liver, leading to the improvement of non-alcoholic steatohepatitis (NASH)." (PMID 38396635, 2024). "Moreover, in a methionine and choline deficient (MCD) diet-induced mouse model of non-alcoholic steatohepatitis (NASH), activation of SIRT1 inhibited NF-κB signaling pathway and exerted anti-steatotic, anti-inflammatory, and anti-apoptotic effects." (PMID 41281762, 2025). "Similarly, treatment with Moringa oleifera prevented liver damage and nonalcoholic steatohepatitis (NASH) progression via SIRT1 upregulation and miR-21a-5p, miR-103-3p, miR-122-5p, and miR-34a-5p downregulation." (PMID 38201989, 2024). "For instance, miR-29a via modulating the GSK-3β/SIRT1 could ameliorate mouse non-alcoholic steatohepatitis." (PMID 37441551, 2023). "Moreover, other authors hinted that rosmarinic acid, which we discussed in more detail, demonstrated anti-inflammatory and anti-apoptotic effects in a mouse model of nonalcoholic steatohepatitis, possibly due to stimulating SIRT1-mediated pathways." (PMID 36145799, 2022).
preeclampsia (15 papers, 2020 to 2026). Preeclampsia is a hypertensive disorder of pregnancy that is characterized by new-onset hypertension with proteinuria presenting after 20 weeks of gestation, and depending on mild or severe forms may initially present with severe headache, visual disturbances, and hyperreflexia. "In a previous study, we identified the association of rs7895833 of the SIRT1 gene with the risk of developing preeclampsia in carriers of the genotype containing the SIRT1 G allele in a heterozygous state." (PMID 40243583, 2025). "The diagnostic value of serum SIRT1 levels combined with uterine artery hemodynamic parameters in the diagnosis of disease severity in patients with preeclampsia was analyzed by ROC curve and AUC." (PMID 39139170, 2024). "We found that serum SIRT1 levels combined with uterine artery hemodynamic parameters has a higher diagnostic value for the severity of preeclampsia compared to the levels of serum SIRT1 or uterine artery hemodynamic parameters." (PMID 39139170, 2024). ", suggesting that serum SIRT1 levels combined with uterine artery hemodynamic parameters has a high diagnostic value for the severity of preeclampsia." (PMID 39139170, 2024). ", suggesting that serum SIRT1 levels combined with uterine artery hemodynamic parameters has a high diagnostic value for fetal growth restriction in preeclampsia." (PMID 39139170, 2024). "The diagnostic value of serum SIRT1 levels combined with uterine artery hemodynamic parameters for fetal growth restriction in patients with preeclampsia was analyzed by ROC curve and AUC." (PMID 39139170, 2024). "Therefore, we evaluated Sirtuin-1 (SIRT1) concentration in plasma from healthy pregnant (HP) women, gestational hypertensive women (GH), and preeclampsia women (PE) via enzyme-linked immunosorbent assay (ELISA)." (PMID 32411327, 2020). "The SIRT1 variant rs12778366 is associated with shorter telomeres and an increased risk of developing preeclampsia, suggesting it may be a useful biomarker for preeclampsia risk assessment in GDM pregnancies." (PMID 40243583, 2025). "Research into polymorphisms of the promoter region of the SIRT1 gene, such as rs12778366 and rs3758391, has revealed several associations with T2DM, obesity, glucose tolerance, hypertension development risk, and preeclampsia." (PMID 40869934, 2025). "We explored the clinical value of serum SIRT1 combined with uterine hemodynamics in preeclampsia in predicting disease severity and fetal growth restriction." (PMID 39139170, 2024). "Unsupervised PCA analysis of the severity of preeclampsia with serum SIRT1 levels combined with uterine arterial hemodynamics showed that groups of different severity tended to be clustered and tended to be discrete." (PMID 39139170, 2024). "Serum SIRT1 combined with uterine hemodynamic parameters in preeclampsia is closely related to disease severity and fetal growth restriction, and is expected to become potential biomarkers for early clinical intervention in patients." (PMID 39139170, 2024). "Levels of p62 remained higher and levels of SIRT1 lower in preterm compared to term infants after additional adjustment for preeclampsia, gestational diabetes, antibiotic use during the last twelve weeks of pregnancy and chorioamnionitis." (PMID 38811718, 2024). "Another study reported a significant decrease in levels of protective proteins such as Sirtunin1 (SIRT1) in placentas from preeclampsia resulting in shorter telomeres." (PMID 38102621, 2023). "Reduced levels were observed in pregnant women developing preeclampsia compared to women with healthy pregnancies, possibly due to increased oxidative stress, endothelial impairment and a reduction in SIRT1 expression." (PMID 36979007, 2023). "A recent study has demonstrated that treatment of recombinant SIRT1 protein can decrease maternal blood pressure and improves angiogenic imbalance, inflammation, and pregnancy outcome in a rat model of preeclampsia." (PMID 37043045, 2023).
preeclampsia (continued). "Recently, the effects of sirtuin 1 (SIRT1) on the biological functions of trophoblasts and endothelial cells have gradually emerged, and the serum and placental level of SIRT1 is reduced in preeclampsia." (PMID 37043045, 2023). "More importantly, SIRT1 protein expression in placental tissue of gestational hypertension rats increased by paeoniflorin treatment in dose-dependent manner." (PMID 35030965, 2022). "There are few reports on SIRT1 in preeclampsia, and data on the metformin effect on SIRT1 in preeclampsia are, so far, unavailable." (PMID 34202343, 2021). "However, to date, the roles of serum SIRT1 and uterine hemodynamics in the progression of preeclampsia are not fully understood." (PMID 39139170, 2024). "The aim of this study was to discover the effect and correlation of serum SIRT1 combined with uterine hemodynamic parameters on disease severity and fetal uterine growth restriction in the progression of preeclampsia, and to evaluate its clinical value as a potential marker." (PMID 39139170, 2024). "Resveratrol-induced SIRT1 activation abrogates senescence in trophoblast-derived BeWo cells in vitro, suggesting the beneficial effect of resveratrol in ameliorating placental senescence in preeclampsia." (PMID 37043045, 2023). "Thus, esomeprazole can suppress preeclampsia-like symptoms by inhibiting excessive placental autophagy in PE, acting via the SIRT1/AMPKα-mTOR pathway." (PMID 35091806, 2022). "In addition, paeoniflorin promoted the expressions of SIRT1 and NO/eNOS and inhibited the production of iNOS in gestational hypertension rats to improve vascular endothelial cell injury." (PMID 35030965, 2022). "In conclusion, paeoniflorin could improve gestational hypertension development by upregulating SIRT1." (PMID 35030965, 2022). "Importantly, we found that SIRT1 levels were reduced in pregnant who subsequently develop preeclampsia (case) compared to control (p < 0.05)." (PMID 32411327, 2020). "There is evidence that SIRT1 may be involved in the development of preeclampsia." (PMID 40243583, 2025). "The heat map of cluster analysis showed that the mild group and the severe group were hierarchically clustered, suggesting that serum SIRT1 levels combined with uterine artery hemodynamic parameters could discriminate disease severity in patients with preeclampsia." (PMID 39139170, 2024). "Cluster analysis heat map showed that the combined and uncombined groups were hierarchically clustered, suggesting that serum SIRT1 levels combined with uterine artery hemodynamic parameters could differentiate fetal growth restriction in patients with preeclampsia." (PMID 39139170, 2024). "SIRT1 decreases the levels of HMGB1 and HSP70 released from IL-6 induced human umbilical vein endothelial cells (HUVECs) and preeclampsia patient serum." (PMID 35030965, 2022).
disc degeneration (14 papers, 2011 to 2026). "MRI and CT analyses demonstrated that enhanced SIRT‐1 activity significantly attenuated disc degeneration and restored intervertebral disc height." (PMID 40891515, 2026). "SIRT1 activation has been shown to postpone disc degeneration, downregulate apoptosis, and preserve extracellular matrix in IVDD; however, the interplay between SIRT1-induced autophagy and disc functionality remains ambiguous." (PMID 40846953, 2025). "Orientin downregulates oxidative stress-mediated endoplasmic reticulum stress and mitochondrial dysfunction through the AMPK/SIRT1 pathway in rat NP and attenuates disc degeneration." (PMID 38553713, 2024). "The present research also revealed that the expression of SIRT1 in clinical NP samples gradually decreased, whereas the extent of cellular senescence was enhanced as disc degeneration intensified." (PMID 32687063, 2020). "SIRT1 affected both extracellular matrix metabolism and proliferation activity; the effect of SIRT1 was altered according to disease class and disc degeneration grade." (PMID 22152608, 2011). "The aims of the present study were to verify the expression of SIRT1 by human IVD cells, to elucidate the function of SIRT1 in IVD cell homeostasis, and to examine the relationship of SIRT1 to disc degeneration." (PMID 22152608, 2011). "SIRT1 mRNA expression increased significantly with donor age and was seen most strongly in early grade 3 disc degeneration." (PMID 22152608, 2011). "SIRT1 treatment significantly reduced aggrecan, Sox9 and collagen type 2 mRNA expression in a dose-dependent manner in all disease classes and disc degeneration grades." (PMID 22152608, 2011). "Overexpression of SIRT1 could mitigate some limitations in MSC survival and adaptation under the severe conditions of disc degeneration, potentially due to SIRT1-mediated anti-ferroptosis effects in MSCs." (PMID 39897051, 2025). "Additionally, melatonin has been shown to inhibit M1 polarization and alleviate disc degeneration by upregulating SIRT1 expression and modulating the SIRT1/Notch pathway." (PMID 40584964, 2025). "First, we tested whether there was a relationship between SIRT1 expression in NP cells and disc degeneration." (PMID 34222486, 2021). "Finally, to seek for potential therapeutic targets for apoptosis in disc degeneration, we performed immunohistochemistry for antiapoptotic Bcl-2 and SIRT1." (PMID 24472667, 2014). "The deterioration of the internal environment prior to early disc degeneration may thus induce SIRT1 expression." (PMID 22152608, 2011). "SIRT1 might be induced in the early disc degeneration stage when the disc internal environment begins to deteriorate from a disturbance in the nutrient supply." (PMID 22152608, 2011). "We suggest that SIRT1 may play a key role in the early stage of disc degeneration in human IVD tissues." (PMID 22152608, 2011). "Thus, the consistently decreased Bcl-2 and SIRT1 expression may contribute to the acceleration of apoptotic cell death in static compression-induced disc degeneration." (PMID 24472667, 2014). "In conclusion, the composite hydrogels could improve the disc microenvironment by clearing intracellular ROS and promoting antioxidant and autophagy activity through the SIRT1/NRF2 pathway, thus showing potential in the treatment of disc degeneration." (PMID 38786250, 2024). "SIRT1 inhibits MCP1 production in degenerating NP cells by inhibiting the phosphorylation of c-Fos and c-Jun factors in activator protein 1 and thus inhibits disc degeneration." (PMID 38553713, 2024). "Our data is the first to indicate that both the percentage of LC3 and SIRT1 positive cells decreased in the NP tissues of severe IDD group, which suggested negative correlation between SIRT1 expression as well as autophagic level and the degree of disc degeneration." (PMID 33363176, 2020).